HOTAIRM1 (HOXA transcript antisense RNA, myeloid-specific 1)
Diseases named in the same sentence as HOTAIRM1 in open-access papers (continued):
Sharing a sentence is not in itself a finding about the gene and the disease.
Sepsis (continued). "In summary, KDM6A demethylase activity is a potential therapeutic target in sepsis MDSCs, acting in part by driving Hotairm1 transcription." (PMID 35185915, 2022). "Mechanistically, KDM6A demethylates the transcription repressive H3K27me3 mark that is deposited on the Hotairm1 promoter as sepsis progresses to the later, protracted state." (PMID 35185915, 2022). "In early sepsis (< day 5), the protein S100A9 was mostly confined to the cytosol, however, Hotairm1 causes a nuclear translocation of S100A9 in late sepsis, resulting in an immunosuppressive phenotype of Gr1+CD11b+MDSCs." (PMID 33807302, 2021). "Together, these results indicate that Hotairm1 mediates S100A9 protein localization in the nucleus in Gr1+CD11b+ MDSCs in late sepsis." (PMID 33335790, 2020). "In support of translating the mechanistic concept to human sepsis, we found that Hotairm1 binds S100A9 protein in CD33+CD11b+HLA-DR− MDSCs during established sepsis." (PMID 33335790, 2020). "Using qPCR, we observed an 18-fold increase in Hotairm1 in exosomes from late sepsis Gr1+CD11b+ cells versus 2-fold in early sepsis cells." (PMID 33335790, 2020). "Mechanistically, increased expression of Hotairm1 associates with its binding to and shuttling S100A9 protein from the cytosol to the nucleus in MDSCs after early sepsis response." (PMID 33335790, 2020). "Late sepsis Gr1+CD11b+ cells with Hotairm1 knockdown were co-cultured with CD4+ T cells isolated from spleens of naive mice." (PMID 33335790, 2020). "The CD4+ T cells were co-cultured with naive Gr1+CD11b+ cells, which cannot suppress T cell, in the presence of exosomes purified from cultures of late sepsis Gr1+CD11b+ MDSCs in which Hotairm1 was knocked down first." (PMID 33335790, 2020). "A 29-fold increase in Hotairm1 transcripts occurred in total RNA extracted from late sepsis Gr1+CD11b+ cells and a 13-fold increase in plasma exosomes from late septic mice (data not shown)." (PMID 33335790, 2020). "Knockdown of Hotairm1 in late sepsis Gr1+CD11b+ MDSCs attenuated their suppressive effects on CD4+ T cells." (PMID 33335790, 2020). "Recent evidence suggests increased expression of HOTAIRM1 in cardiomyocytes treated in vitro with LPS or those isolated from mice receiving LPS to induce sepsis." (PMID 29147069, 2017). "Epigenetic modifications, such as H3K27me3 demethylation and H3K4me3 activation, dynamically regulate the transcription of the long non-coding RNA Hotairm1 gene, thereby programming MDSCs function and driving their pathological accumulation during late-stage sepsis." (PMID 40832104, 2025). "For instance, HOTAIRM1 inhibitors have been developed to block the upregulation of PD-1 in T-cells, thereby reversing T-cell exhaustion and improving immune function in preclinical models of sepsis." (PMID 39594987, 2024). "LncRNA HOTAIRM1 is highly expressed in late phase of sepsis in a mouse model; it could induce T cell exhaustion by increasing the percentage of PD-1+ T cells and regulatory T cells." (PMID 36817490, 2023). "Notably, Hotairm1 transcripts were detected in the S100A9 protein complex at a significantly higher level in late sepsis Gr1+CD11b+ cells." (PMID 39665047, 2023). "We determined whether the increase in S100A9 phosphorylation following Hotairm1 knockdown decreased IL-10 levels in late sepsis Gr1+CD11b+ cells." (PMID 39665047, 2023). "Although S100A9 is mainly known as a soluble inflammatory mediator/alarmin that enhances the inflammatory responses, our studies suggest that, in the context of late sepsis, Hotairm1 can switch S100A9 protein into a nuclear co-factor that supports the MDSC phenotype." (PMID 39665047, 2023). "PCR analysis of the immunoprecipitated RNA showed that increasing Hotairm1 transcripts in early sepsis Gr1+CD11b+ cells increased the amount of S100 protein binding, whereas Hotairm1 knockdown in late sepsis Gr1+CD11b+ cells significantly reduced S100A9 binding." (PMID 39665047, 2023).
Sepsis (continued). "Because siRNA-mediated knockdown of Hotairm1 in late sepsis Gr1+CD11b+ cells increased S100A9 phosphorylation by p38 MAPK, we investigated whether inhibition of KDM6A demethylase activity can affect S100A9 protein phosphorylation." (PMID 39665047, 2023). "In summary, Hotairm1 prevents the phosphorylation of S100A9 protein in MDSCs during late sepsis." (PMID 39665047, 2023). "Additionally, we performed protein-RNA co-immunoprecipitation and PCR analysis in late sepsis Gr1+CD11b+ cells following Hotairm1 knockdown by siRNA." (PMID 39665047, 2023). "Notably, increasing S100A9 protein phosphorylation in late sepsis MDSCs via Hotairm1 knockdown decreases the production of the immunosuppressive cytokine IL-10." (PMID 39665047, 2023). "Potential impact of this study is that epigenetic targeting of Hotairm1 might alleviate the sepsis-induced immunosuppression during MDSC expansion." (PMID 39665047, 2023). "Our findings support that Hotairm1 targeting is a likely treatment path for protracted sepsis." (PMID 35185915, 2022). "Hotairm1 may provide a molecular targeting site for post-acute sepsis correction of immune suppression." (PMID 33335790, 2020). "The major finding of this study is that Hotairm1 dependent translocation of S100A9 protein from the cytosol to the nucleus in Gr1+CD11b+ myeloid precursors predominates during the late/chronic stage of sepsis and supports the MDSC repressor function." (PMID 33335790, 2020). "Importantly, we observed significant increases in Hotairm1 levels in late sepsis Gr1+CD11b+ cells as well as in exosomes derived from their culture compared with early sepsis Gr1+CD11b+ cells." (PMID 33335790, 2020). "In addition, Hotairm1 was detected at high levels in naive Gr1+CD11b+ cells after culturing with exosomes derived from late sepsis Gr1+CD11b+ cells." (PMID 33335790, 2020). "Together, these data support that Hotairm1 is a plausible molecular target for treating late sepsis immune suppression in humans and its immune repressor mechanism may be cell autonomous." (PMID 33335790, 2020). "Thus, the elevated levels of Hotairm1 suggest that its expression is part of the immunopathological response to sepsis." (PMID 33335790, 2020). "We tested whether increasing Hotairm1 levels in early sepsis Gr1+CD11b+ MDSCs could affect Arginase 1 and IL-10 expressions." (PMID 33335790, 2020). "Importantly, Hotairm1 knockdown in late sepsis Gr1+CD11b+ MDSCs prevented S100A9 cytosol to nuclear transfer and decreased repression of proimmune T cells." (PMID 33335790, 2020). "Here, we found differential expression of myeloid-related lncRNA Hotairm1 in late sepsis." (PMID 33335790, 2020). "Notably, ectopic expression of Hotairm1 in early sepsis Gr1+CD11b+ cells shuttled S100A9 to the nucleus and promoted the MDSC repressor phenotype." (PMID 33335790, 2020). "Importantly, the depletion of Hotairm1, which facilitatesS100A9 nuclear accumulation, significantly reduced IL-10 andTGF-β production, further reinforcing the therapeutic potential of targetingS100A9 to mitigate sepsis-induced immunosuppression." (PMID 40458301, 2025). "By identifying patients who exhibit epigenetic markers of immune suppression, such as the hypermethylation of pro-inflammatory genes or the upregulation of non-coding RNAs like HOTAIRM1, clinicians could tailor treatments to restore immune competence in sepsis survivors." (PMID 39594987, 2024). "As sepsis enters a late phase response,MDSCs lose their ability to secrete S100A9, as it becomesdephosphorylated due to binding to Hotairm1 and moves from thecytosol to the nucleus." (PMID 40458301, 2025). "Hotairm1 couples with theinflammatory protein S100A9 and shuttles it from the cytosol to thenucleus during late sepsis." (PMID 40458301, 2025). "The present study shows that Hotairm1 prevents the phosphorylation of S100A9 protein in MDSCs in mice and humans with protracted sepsis." (PMID 39665047, 2023).
Sepsis (continued). "The inhibition of S100A9 phosphorylation in late sepsis Gr1+CD11b+ cells mirrored the significant increases in Hotairm1 binding to S100A9 protein, as demonstrated by the increase in Hotairm1 transcripts in the immunoprecipitated protein complex." (PMID 39665047, 2023). "During late sepsis, the histone demethylase KDM6A catalyzes the removal of H3K27me3, leading to PU.1 binding and activation of Hotairm1 transcription." (PMID 39665047, 2023). "During late sepsis, S100A9 protein moves from the cytosol to the nucleus in Gr1+CD11b+ MDSCs, concurrent with increases in Hotairm1 transcripts, and knockdown of Hotairm1 results in the shuttling of S100A9 protein back to the cytosol." (PMID 39665047, 2023). "Protein-RNA co-immunoprecipitation and PCR, analysis of the immunoprecipitated RNA, showed low levels of Hotairm1 RNA binding to S100A9 protein in MDSCs from early septic patients, and the amount of Hotairm1 binding significantly increased during late sepsis." (PMID 39665047, 2023). "Using a mouse model that simulates the immunobiology of sepsis, we find that histone demethylase KDM6A promotes Hotairm1 transcription by demethylating transcription repression H3K27me3 histone mark." (PMID 35185915, 2022). "PCR of cross-linked RNA extracted from S100A9 immunoprecipitates showed that Hotairm1 binds to S100A9 protein and transfers it from cytosol to nucleus in late sepsis Gr1+CD11b+ cells." (PMID 33335790, 2020). "Our results suggest that Hotairm1 dysregulates S100A9 protein function and activity by phosphorylation, which could inform sepsis therapeutic targeting." (PMID 39665047, 2023). "We reported that Ezh2 binds at Hotairm1 promoter in MDSCs with no change in binding levels before and during sepsis, but Ezh2 knockdown reduces H3K27me3 levels on Hotairm1 promoter." (PMID 35185915, 2022). "Mechanistically, increased Hotairm1 expression in MDSCs in mice converted S100A9 from a secreted proinflammatory mediator to an immune repressor by binding to and shuttling it from cytosol to nucleus during late sepsis." (PMID 33335790, 2020). "Notably, lncRNA Hotairm1 (HOXA transcript antisense RNA, myeloid-specific 1) markedly increased in Gr1+CD11b+ cells after early sepsis." (PMID 33335790, 2020). "To test whether Hotairm1 can bind S100A9 protein, we performed RNA-immunoprecipitation with cell lysates from late sepsis Gr1+CD11b+ cells." (PMID 33335790, 2020). "Notably, the knockdown of Hotairm1 in late sepsis MDSCs results in the re-relocalization of S100A9 in the cytosol, suggesting that Hotairm1 may facilitate S100A9 nuclear localization in MDSCs during sepsis." (PMID 39665047, 2023). "In addition, late sepsis Gr1+CD11b+ MDSCs with Hotairm1 knockdown could not inhibit T cells activation and proliferation." (PMID 33335790, 2020).
acute promyelocytic leukemia (14 papers, 2015 to 2023). An aggressive form of acute myeloid leukemia (AML), characterized by arrest of leukocyte differentiation at the promyelocyte stage, due to a specific chromosomal translocation t(15;17) in myeloid cells. "In human acute promyelocytic leukemia, HOTAIRM1 knockdown inhibits NB4 granulocyte cells differentiation by maintaining cells in the G1 phase and by regulating integrin gene expression levels." (PMID 35087800, 2021). "Knockdown of HOTAIRM1 in the human acute promyelocytic leukemia (APL) cell line NB4 resulted in decreased granulocytic maturation." (PMID 32164715, 2020). "In acute promyelocytic leukemia, HOTAIRM1, an intergenic lncRNA, was proved to regulate cell proliferation." (PMID 32067385, 2020). "It was reported that HOTAIRM1 enhanced the autophagy in acute promyelocytic leukemia and contributed to the suppression of colorectal cancer." (PMID 31920490, 2019). "In addition, Hotairm1 is significantly increased during retinoic acid-induced granulocytic differentiation of the NB4 human acute promyelocytic leukemia cell line." (PMID 33335790, 2020). "In addition, HOTAIRM1 regulates cell cycle progression during myeloid maturation in the NB4 human promyelocytic leukemia cell line." (PMID 26436590, 2015). "In acute promyelocytic leukemia (APL)-ascites mouse model and APL cell lines, lncRNA HOTAIRM1 facilitates formation of autophagosome to degrade oncoprotein PML nuclear body scaffold (PML)-retinoic acid receptor alpha (RARA) via targeting miR-20a." (PMID 34722769, 2021). "Long noncoding RNA HOX antisense intergenic RNA myeloid 1 (HOTAIRM1) has been characterized as a critical factor in all-trans retinoic acid (ATRA)-induced differentiation of acute promyelocytic leukemia (APL) cells." (PMID 27146823, 2016). "In addition, the low expression of HOTAIRM1 is observed in acute promyelocytic leukemia (APL)." (PMID 27146823, 2016). "The study showed a decrease in the HOTAIRM1 expression in APL (acute promyelocytic leukemia) leading to the inhibition of all-trans-retinoic acid (ATRA) mediated degradation of PML-RARA causes repression of promyelocytic to granulocytic cellular differentiation." (PMID 34303380, 2021). "HOTAIRM1 expression is specific to the myeloid lineage and is upregulated during the retinoic acid (RA)-promoted granulocytic differentiation of NB4 promyelocytic leukemia and human normal hematopoietic cells." (PMID 34502451, 2021). "Additionally, in ATRA-induced differentiation of acute promyelocytic leukemia (APL) cells, it has been revealed that PU.1 constitutively binds to the regulatory region of HOTAIRM1, which leads to the transactivation of the regulatory region of HOTAIRM1." (PMID 27680332, 2016). "A recent study has shown that HOTAIRM1 can enhance autophagosome formation to degrade oncoprotein PML–RARA by sponging miR-20a to upregulate ULK1 in acute promyelocytic leukemia (APL)-ascites mouse model and APL cell lines." (PMID 33050642, 2020).
colorectal cancer (13 papers, 2016 to 2023). A primary or metastatic malignant neoplasm that affects the colon or rectum. "A multitude of evidence indicates that HOTAIRM1 play vital role in neural differentiation and is a potential diagnostic biomarkers of colorectal cancer." (PMID 30309340, 2018). "Interestingly, we identified a previously reported lncRNA species (HOTAIRM1) that is associated with colorectal cancer." (PMID 32033141, 2020). "For example, the HOTAIRM1 gene has been identified as a potential biomarker for diagnosis of colorectal cancer." (PMID 36289596, 2022). "Some studies have reported that MEG3 9, lnc-ATB 10 and BLACAT1 11 were up-expressed in colorectal cancer plasma, while NKILA 7 and HOTAIRM1 12 were down-regulated in colorectal cancer tissue." (PMID 32742499, 2020). "For instance, HOTAIRM1 inhibits tumorigenesis by forming ceRNA networks in colorectal cancer, head and neck tumors, gastric cancer, and hepatocellular carcinoma." (PMID 31477638, 2019). "Recent studies have shown that HOTAIRM1 is involved in acute myeloid leukemia and colorectal cancer." (PMID 30376874, 2018). "Here, we found that expression of HOTAIRM1 was reduced in colorectal cancer (CRC) tissues compared with matched normal tissues, and plasma HOTAIRM1 levels in CRC patients were less than in controls." (PMID 27307307, 2016). "However, HOTAIRM1 is downregulated in the hepatocellular carcinoma 40, colorectal cancer 44, 45, ovarian cancer 46 and GC 28, and is absolutely a suppressor factor." (PMID 35711826, 2022). "It meant that HOTAIRM1 played a role of tumour suppressor in colorectal cancer." (PMID 30453964, 2018). "Recently, HOTAIRM1 was found lowly expressed in tissues and plasma of colorectal cancer and may be as a potential biomarker for diagnosis of colorectal cancer." (PMID 30376874, 2018). "The interaction between HOTAIRM1 and SFPQ is a promising diagnostic biomarker of colorectal cancer." (PMID 30309340, 2018). "In addition, HOTAIRM1 can interact with SFPQ in colorectal cancer (CRC) tissues that release PTBP2 from the SFPQ or PTBP2 complex." (PMID 30309340, 2018). "Occasionally, we found that HOTAIRM1 could also be detected in colon tissues; therefore, we investigated the expression and function of HOTAIRM1 in colorectal cancer (CRC)." (PMID 27307307, 2016).